INS (insulin)
Diseases named in the same sentence as INS in open-access papers (continued):
Sharing a sentence is not in itself a finding about the gene and the disease.
diabetes (continued). "Our studies indicate that lowered interstitial fluid pH occurs in diabetes mellitus, causing insulin resistance via reduction of the binding affinity of insulin to its receptor." (PMID 30347717, 2018). "Embryonic deletion of the Manf gene in mice led to gradual postnatal development of insulin-deficient diabetes caused by reduced beta cell proliferation and increased beta cell death due to increased and sustained ER stress." (PMID 30386256, 2018). "Experimental diabetes studies showed that insulin deficiency resulted in decreased expression of GH receptors, which was restored by insulin treatment with normalized level of IGF-1." (PMID 30297647, 2018). "Type 1 diabetes mellitus (T1DM) is characterized by insulin-deficient production leading to hyperglycemia, which is associated with diabetic complications such as cardiovascular diseases." (PMID 29796316, 2018). "The characteristic of diabetes is that the blood glucose is higher than the normal level, which is caused by defective insulin secretion or its impaired biological effects, or both." (PMID 30459809, 2018). "Diabetes mellitus (DM) is a chronic and common metabolic disease with a worldwide prevalence and is associated with high glucose and a deficit in insulin production or sensitivity." (PMID 30544722, 2018). "Diabetes, caused by insulin production disturbance, is considered as the most common metabolic disorder all over the world." (PMID 30595825, 2018). "In this population-based study of middle-aged women free of diabetes mellitus at baseline, the 34-year risk of dementia was more than doubled in women with initially low fasting serum insulin compared to women with medium insulin values." (PMID 29997193, 2018). "Diabetes is a chronic metabolic disease mainly caused by insulin dysfunction and pancreatic β-cell failure." (PMID 30140229, 2018). "Type II diabetes mellitus (T2DM), which is caused by increased insulin resistance and decreased insulin secretion, accounts for 90–95% of people with diabetes." (PMID 30424007, 2018). "Although epidemiological studies show that diabetes is a risk factor for AD, there are still discrepancies about how insulin sensitivity modulates hyperphosphorylation of tau." (PMID 29743868, 2018). "Because multiple tissues are affected by systemic alterations in insulin signaling, the functional locus of insulin signaling in diabetes-associated hypersensitivity remains obscure." (PMID 29752280, 2018). "Estimates of the TURN varied widely across drug-indication groups, ranging from risk considered unacceptable with 1 daily dose missed per month (e.g., insulin for diabetes) to risk always considered acceptable (e.g., anti-dementia drugs)." (PMID 30543701, 2018). "The identification of the tails of the U-shaped risk curve for insulin and dementia with distinct mechanisms was possible because of the long follow-up and by comparing the associations of insulin with different dementia endpoints and diabetes mellitus." (PMID 29997193, 2018). "Ninety percent of diabetes is type 2 diabetes, generally with obesity, deficiency in insulin secretion, and insulin resistance." (PMID 30301245, 2018). "Our results demonstrate that neonatal diabetes-associated INS-mutations lead to defective beta-cell mass expansion, contributing to diabetes development." (PMID 30412052, 2018). "Impairment of insulin-stimulated glucose uptake by fat and muscle during diabetes causes blood levels of glucose concentrations to remain high." (PMID 30563087, 2018). "Though, a high concentration of insulin has a negative impact on the β-cells physiological function and the decrease in insulin activity in body ultimately causes diabetes." (PMID 30524692, 2018). "Diabetes mellitus is a group of metabolic disorders characterized by hyperglycemia associated with absolute or relative deficiencies in insulin secretion or insulin action resulting in alteration of carbohydrate, fat, and protein metabolism." (PMID 30258612, 2018).
diabetes (continued). "Earlier, it was demonstrated that patients with HNF1α mutations develop diabetes after the first decade, preceded by abnormal glucose-induced insulin secretion." (PMID 29867778, 2018). "Maternal diabetes and obesity induce marked abnormalities in glucose homeostasis and insulin secretion in the fetus, and are linked to obesity, diabetes, and metabolic disease in the offspring, with specific metabolic characterization based on offspring sex." (PMID 30201937, 2018). "Duration of diabetes, A1C, male gender, macroalbuminuria, and insulin therapy were found to be strongly associated with increased risk of DR among South Indians." (PMID 29527102, 2018). "In diabetes mellitus, reduction of glucose uptake into the cells owing to deficiency of insulin signal enhances β‐oxidation of fatty acids and results in further generation of ketone bodies as a byproduct." (PMID 30258609, 2018). "Type 2 diabetes is the most common form of diabetes and ranges from insulin resistance, relative insulin deficiency to prevailing defective insulin secretion." (PMID 29394254, 2018). "Diabetes is a chronic metabolic disorder characterized by hyperglycemia and reduced glucose utilization due to defective insulin secretion or action." (PMID 30425651, 2018). "The 2009 American Diabetes Association consensus statement recommends either a 0.1 unit/kg/intravenous (IV) regular insulin bolus followed by a 0.1 unit/kg/h IV regular insulin infusion, or a 0.14 unit/kg/h IV regular insulin infusion." (PMID 30544554, 2018). "Cultural beliefs can influence insulin adherence negatively, particularly when cultural traditions conflicted with the underlying constructions about what insulin was and how diabetes should be treated." (PMID 29788908, 2018). "There is a widely acknowledged association between insulin resistance and obesity/type 2 diabetes (T2DM), and insulin sensitizing treatments have proved effective in preventing diabetes and inducing weight loss." (PMID 29747432, 2018). "Pharmacologically inhibiting mitochondrial fission by the Drp1 inhibitor, mdivi-1, also rescued mitochondrial network, reduced mtROS, and improved insulin signaling of diabetes-susceptible cybrid cells." (PMID 30363990, 2018). "Diabetes mellitus is a metabolic disorder characterized by hyperglycemia, caused by adeficit in the secretion or function of insulin." (PMID 29694509, 2018). "Diabetes is associated with reduced insulin secretion or action, which results in an increased catabolic state with breakdown of body tissue and loss of calories leading to weight loss." (PMID 30345114, 2018). "Two major types of diabetes are known, type 1 and type 2, characterized by insulin defects such as insulin deficiency and insulin resistance, respectively." (PMID 29558444, 2018). "It is also expressed in the early pancreatic bud and is necessary for insulin homeostasis in the adult pancreas; Pax6 deletion rapidly leads to classical diabetes and weight loss." (PMID 30007277, 2018). "In participants with diabetes, we found a positive association between self-reported insulin use and experienced diabetes burden, adjusted for the other variables." (PMID 29347915, 2018). "The pathogenesis of type 2 diabetes mellitus (T2DM) is closely associated with mitochondrial functions in insulin-responsive tissues." (PMID 30266947, 2018). "The low number of Swedes with less than 1% having both parents and siblings, single parent and siblings, parents and children affected by diabetes made it impossible to study the risk of family clustering on insulin secretion and action." (PMID 29274011, 2018). "Hypoglycaemic events associated with insulin, particularly nocturnal hypoglycaemia, were reported as having a disrupting effect on: diabetes self-management; sleep quality and next-day functioning; work performance and driving; and personal well-being." (PMID 29788908, 2018).
diabetes (continued). "Adult Akita mice develop severe insulin-deficient diabetes with fed blood glucose ~ 400 mg/dl along with a 90% decrease of pancreatic insulin content." (PMID 30412050, 2018). "After multivariate adjustment (model 2), all markers, except fasting insulin, were significantly associated with diabetes incidence." (PMID 29018885, 2018). "Diabetes mellitus is a chronic disease caused by inherited and/or acquired deficiency in production of insulin by the pancreas or by the ineffectiveness of the insulin produced." (PMID 29507593, 2018). "Type 1 diabetes mellitus (T1DM) is a multifactorial disease that is characterized by insulin deficiency due to destruction of the insulin producing pancreatic beta (β)-cells." (PMID 30285704, 2018). "The bulking and soluble, viscous fibers from both fresh and dried fruits help to attenuate postprandial insulin responses to protect against the risk of insulin resistance and β-cells dysfunction and senescence, major factors in developing diabetes." (PMID 30487459, 2018). "Insulin is the main therapy for type 1 diabetes (diabetes characterised by absolute insulin deficiency) and it is also sometimes used for therapy of type 2 diabetes (diabetes characterised by relative insulin deficiency and/or insulin resistance)." (PMID 30211323, 2018). "Medications, particularly the use of insulin, were linked to many participants’ perceived diabetes control." (PMID 30400859, 2018). "The -866AA genotype carriers have decreased glucose-stimulated insulin secretion and have increased risk of diabetes than those GG genotype carriers." (PMID 29849618, 2018). "A previous studies conducted in Finland have reported reduced insulin secretion and increased type 2 diabetes risk among those with a family history of diabetes." (PMID 29274011, 2018). "Insulin-secreting β-cells failure is a common feature of diabetes, which leads to relative or absolute insulin deficiency." (PMID 29671829, 2018). "Disorders in the amount of glucose caused by improper insulin action are the cause of severe illnesses and dysfunctions in humans, which are called diabetes mellitus." (PMID 30042294, 2018). "For example, insulin resistance which is a hallmark of type 2 diabetes mellitus, is characterized by a reduced insulin-mediated activation of the PI3K/Akt pathway regulating glucose uptake." (PMID 29373583, 2018). "(vi) rs1801483 (MAF_KWT:3.78%; MAF_1KGP:0.42%) associated with Diabetes mellitus type 2, non-insulin dependent (a multifactorial complex disorder)." (PMID 30409984, 2018). "Chronically raised blood sugar and associated metabolic disturbances related to insufficiency in insulin production or/and insulin action is the underlying pathology in diabetes mellitus." (PMID 29875963, 2018). "We previously reported that caffeine consumption ameliorates diabetes-induced hippocampal degeneration and prevents diabetes-associated memory deficits in insulin-deficient rats and in a mouse model of obesity-associated type 2 diabetes (T2D)." (PMID 30686981, 2018). "Type 2 diabetes is the more common form of the disease, affecting 90–95% of diabetics, and is characterised by a loss of ability to respond to insulin (i.e. there is insulin resistance, also termed as insulin insensitivity)." (PMID 30509933, 2018). "Especially, the most predominant T2DM which accounts for more than 90% of diabetes is caused by resistance to insulin." (PMID 29546042, 2018). "When GABA is given to mice with T1D, it restores β cells, completely reverses the symptoms of hyperglycemia and cures diabetes, associated with elevated insulin levels and reduced glucagon levels." (PMID 30202421, 2018). "Heterozygous GLUT4+/− mice that display decreased GLUT4 protein in muscle and in adipose tissue are severely insulin resistant and predisposed to diabetes." (PMID 30469501, 2018).
diabetes (continued). "In this study, the prevalence of DME was associated with male gender, diabetes duration, HbA1c ≥ 7.0%, insulin usage, alcohol consumption, low HDL-C levels, nephropathy, neuropathy, severity of DR, and previous cataract surgery." (PMID 29649995, 2018). "Chronic increased insulin demand, e.g., obesity, insulin resistance, β-cell dysfunction and diabetes, predisposes to the onset of metabolic disease that includes adverse cardiac outcomes and CVD." (PMID 30344301, 2018). "Botolin S and McCabe LR found that BADGE treatment prevents diabetes-induced hyperlipidemia, effectively blocks diabetes type I-induced bone adiposity and reduces the induction of adipogenic gene expression in insulin-deficient diabetic BALB/c mice." (PMID 29703208, 2018). "Many studies have shown greater insulin resistance in black Africans and Indians, and higher insulin release to maintain normoglycaemia in black Africans compared with whites, which likely contributes to their greater susceptibility to diabetes." (PMID 30260983, 2018). "Diabetes, caused by inherited and/or acquired deficiency in production of insulin by the pancreas (type 1) or by ineffectiveness of insulin (type 2), is one of the most burdensome and costly chronic disease in the world." (PMID 29710864, 2018). "Diabetes mellitus is a chronic condition of elevated blood glucose levels caused by insufficient insulin production and/or insulin resistance." (PMID 29928283, 2018). "Type 2 diabetes mellitus (T2DM) is a metabolic disease caused by the impaired insulin production and/or decreased tissue response to insulin." (PMID 29686718, 2018). "AD was predicted by low insulin, and this association was strengthened after censoring for diabetes comorbidity." (PMID 29997193, 2018). "Diabetes is associated with increased oxidative stress in metabolic tissues and excessive production of reactive oxygen species negatively affects insulin responses." (PMID 29299636, 2018). "Four of these modules were significantly associated with the diabetes-related traits (week 15 and week 16 weight, glucose tolerance, insulin tolerance, serum glucose and insulin levels, and food consumption)." (PMID 29447215, 2018). "The protective mechanisms associated with whole fruits and lower diabetes risk include improved weight control, satiety, glucose tolerance, insulin sensitivity, microbiota ecosystem health and reduced systemic inflammation." (PMID 30487459, 2018). "There are some similarities in the pathogenesis of the increased BCAAs in diabetes and short-term starvation, which is also an insulin deficient state." (PMID 29755574, 2018). "The pathogenesis of diabetes is characterized by the progressive development of insulin resistance and a deficiency in insulin secretion, leading to overt hyperglycemia." (PMID 30275974, 2018). "Diabetes mellitus is characterized by absolute or relative deficiencies in insulin secretion and/or insulin action associated with chronic hyperglycaemia and disturbances of carbohydrate, lipid, and protein metabolism." (PMID 29713363, 2018). "Perturbed Akt/PKB signaling has been implicated in several serious ailments, e.g., peripheral INS resistance and diabetes, Alzheimer's and Parkinson's diseases (AD, PD), and cancer." (PMID 29435164, 2018). "Insulin treatment was only associated with IGF1R expression in tumors of premenopausal women with diabetes." (PMID 29486734, 2018). "During recent years, the promising features of miRNAs as biomarkers associated with insulin production, residual β-cell function, and disease complications of diabetes have been investigated." (PMID 30469437, 2018). "We found that insulin treatment in women with diabetes is associated with p-mTOR tumor expression, and in premenopausal women with IGF1R tumor expression." (PMID 29486734, 2018). "Taken together, these publications support the proof of concept that targeting insulin action in diabetes is associated with improvement in VO2 max in uncomplicated T2D." (PMID 29720965, 2018).
diabetes (continued). "The authors note that low acceptance of insulin therapy in patients with diabetes in Taiwan is associated with physician prescribing behavior and patient decision-making based on disease management." (PMID 30143020, 2018). "HNF4A mutations can cause hyperinsulinemic hypoglycemia and macrosomia in the neonatal period, as well as diabetes in adolescence or early adulthood caused by an impaired insulin secretory response to glucose in pancreatic β-cells." (PMID 30005691, 2018). "Clinically, diabetes is caused by a loss of insulin (INS) production/secretion from pancreatic beta cells, or a decreased sensitivity to circulating INS." (PMID 29483633, 2018). "Later on β-cell failure caused by a loss of cells and reduced insulin secretion from remaining individual β-cells leads to overt diabetes." (PMID 30016962, 2018). "The patients with diabetes carrying the KCNQ1 rs2237895 C allele had a smaller change in both fasting insulin level and HOMA-IR." (PMID 30065651, 2018). "Women with IGT and diabetes had an increased clinical risk profile (higher fasting glucose and insulin treatment during pregnancy) and developed diabetes at an earlier gestational age than those who remained normoglycaemic after pregnancy." (PMID 29967793, 2018). "There is strong evidence that maternal obesity and diabetes are associated with higher cord-blood insulin and leptin concentrations." (PMID 29925339, 2018). "The chronic metabolic disorder, diabetes mellitus is caused by deficiency of insulin secretion and/or decreased response of organs to insulin." (PMID 30327602, 2018). "Infants affected by this early onset of diabetes often have mutations in one copy of the gene that encodes insulin." (PMID 30412052, 2018). "Insulin is critical for glucose homeostasis, and insulin deficiency or resistance leads to the development of diabetes." (PMID 30275974, 2018). "The serum-related parameters associated with diabetes phenotype, insulin resistance and insulin secretion of triple-transgenic mice were measured." (PMID 29682407, 2018). "Type-2 diabetes, which accounts for 90–95% of total diabetes cases, is characterized by an increased resistance to insulin action and/or deficiency in insulin secretion." (PMID 29995924, 2018). "Consistent with onset of diabetes, βEedKO-driven loss of insulin immunoreactivity was synchronized and progressive between 8 and 25 weeks of age." (PMID 29754954, 2018). "Diabetes, heart disease, and hypertension messages were correlated with topics that focused on disease management (weight loss, insulin, and reduce stress) and lifestyle choices (diet and exercise)." (PMID 30522989, 2018). "In patients with type 2 diabetes mellitus (T2D), a higher HbA1c and receiving insulin therapy are described to be associated with a more positive evaluation." (PMID 29636042, 2018). "Diabetes is a chronic disease in which insulin production is deficient (Type 1) or resistant (Type 2) leading to organ complications including the heart, kidney, retina, and peripheral nerves." (PMID 31355358, 2018). "Increasing evidence suggests that diabetes is an independent risk factor for HCC, particularly diabetes controlled by diet, insulin or sulfonylureas." (PMID 30463528, 2018). "DM is classified into type 1 diabetes (T1DM), type 2 diabetes (T2DM), gestational DM (GDM), and other specific types of diabetes, based on underlying disease mechanisms and the demand for insulin." (PMID 30104398, 2018). "Zebrafish have an insulin-secreting pancreas and genes related to diabetes – such as those encoding insulin, IA-2 autoantigen and IA-2β autoantigen – have been cloned." (PMID 30158110, 2018). "After additionally adjusting for duration of diabetes and use of insulin injections in model 3, these positive association remained significant." (PMID 29795569, 2018).